ZBTB8B (zinc finger and BTB domain containing 8B)
Description:
May be involved in transcriptional regulation.
Synonyms: RP1-27O5.1; DKFZp547H154; ZNF916B
Tractability: No criterion of Open Targets' tractability assessment is met for any kind of drug.
Gene: Protein-coding gene on chromosome 1 (32,465,050 to 32,496,686, forward strand). Ensembl gene ENSG00000273274.
Subcellular location: Nucleus
Subcellular location (Human Protein Atlas): Nucleoplasm; Cytosol
Gene Ontology:
Molecular function: protein binding; DNA-binding transcription factor activity, RNA polymerase II-specific
Biological process: regulation of transcription by RNA polymerase II
Cellular component: cytosol; nucleoplasm; chromatin; nucleus
Genetic constraint (gnomAD): Loss-of-function variants: 20 observed, 34.55 expected, observed/expected ratio (o/e) 0.58, 90% interval 0.41 to 0.84. The upper end of that interval is the gene's LOEUF score, 0.84, which puts it in group 3 of 6, group 1 being the genes least tolerant of losing a copy. Missense variants: 515 observed, 666.45 expected, observed/expected ratio (o/e) 0.77, 90% interval 0.72 to 0.83. Synonymous variants: 248 observed, 262.95 expected, observed/expected ratio (o/e) 0.94, 90% interval 0.85 to 1.05.
Homologues: Orthologues: chimpanzee ZBTB8B (99% identical), macaque ZBTB8B (99% identical), dog ZBTB8B (89% identical), pig ZBTB8B (88% identical), rabbit ZBTB8B (85% identical), rat Zbtb8b (83% identical), mouse Zbtb8b (83% identical), guinea pig ZBTB8B (82% identical), tropical clawed frog zbtb8b (65% identical). Paralogues in human: ZBTB8A (32% identical), ZBTB10 (28% identical), ZBTB22 (19% identical), C17orf113 (18% identical), ZBTB9 (18% identical).
Diseases named in the same sentence as ZBTB8B in open-access papers:
ZBTB8B is named in the same sentence as 1 disease in open-access papers, as found by Europe PMC text mining. Sharing a sentence is not in itself a finding about the gene and the disease.
ZBTB8B shares sentences with these, for which no sentence is quoted: cancer (1 paper).